CD4 (CD4 molecule)
Diseases named in the same sentence as CD4 in open-access papers (continued):
Sharing a sentence is not in itself a finding about the gene and the disease.
infection (continued). "If indeed HIV infection results in increased susceptibility to multiple strain infection, this vulnerability may apply at all CD4 counts, just as HIV-infected patients are more susceptible to TB disease at any CD4 count." (PMID 21143966, 2010). "Although we observed the reconstituted immunity (increase in CD4+ count), it is possible that it may take a longer time to clear any infection, including HPV." (PMID 20946655, 2010). "Simian models of HIV infection demonstrated that the virus establishes its initial reservoirs of infection in resting T cells of the gut associated lymphoid tissue (GALT), and subsequent immune activation due to damage to the gut establishes rampant infection and depletion of CD4+ T cells." (PMID 21994702, 2010). "First, while both CD4-PE and 3B3-PE inhibited spreading infection, the effects were relatively inefficient compared to activities in direct killing assays; at best the viral peak was reduced and delayed and the killing of target cells was slowed, but the effects were never complete." (PMID 20548940, 2010). "The depletion of memory CD4+ T cells, especially in the gut during the acute phase of infection, provide further evidence that the induction of mucosal immunity should be considered a high priority in the development of vaccines against mucosally transmitted HIV-1." (PMID 21994611, 2010). "Peripheral CD4+ T cells rebound to near pre-infection levels." (PMID 20459829, 2010). "BTLA expression increased in CD4+ T cells, peaking on day 10 after infection." (PMID 21042564, 2010). "Secondly, although an increase in CD25+CD4+ T cell suppression early after infection when pathogen proliferation occurs, potential shifts in Treg suppression at later time points during the natural progression of persistent infections has not been previously demonstrated." (PMID 20714351, 2010). "The system-wide activation of CD4+ T cells results in an increased number of infected cells and high viral reproduction that leads to viral peaks observed in the primary stages of the infection." (PMID 20967291, 2010). "In this study, we attempted to identify worm antigens that stimulate CD4+ T cell responses during permissive primary infection, as these antigens may be involved in stimulating responses that facilitate schistosome worm development." (PMID 21078176, 2010). "CCR5 levels are profoundly lower on SM CD4+ T cells compared with RM and humans, which may restrict the target cells available for infection in vivo." (PMID 20865163, 2010). "Upon infection with Ye CD4+ (90%) and to a lesser extent CD8α+ DCs (65%) were lost." (PMID 21124820, 2010). "Anti-HBc alone (in absence of anti-HBs) as a marker of occult infection was seen in 11.3% of samples tested and was associated with lower CD4+ levels below 200 cells/cumm in 84.6% patients (p = 0.032) as compared to higher CD4+ levels." (PMID 20205948, 2010). "Zwitterionic polysaccharide (ZPS) components of the bacterial cell envelope have been shown to exert a major histocompatibility complex (MHC) II-dependent activation of CD4+ T cells, which in turn can modulate the outcome and progression of infections in animal models." (PMID 20949105, 2010). "Thus, we expect that the number of cells required to achieve a practical level of inhibition of infection is likely significantly less than the lower level display of CD4 reportedly observed on other bacteria such as Lactobacilli." (PMID 20442778, 2010). "Since IL-2Jc treatment increased IL-10 and CTLA-4 expression by Foxp3+ CD4+ T cells during infection, we hypothesized that protection was dependent upon these two molecules." (PMID 21170302, 2010). "The selection of high avidity gag-specific CD4+ T cells may result from a lower exposure to HIV antigens during the acute infection stage, when the repertoire of responding T cells is initially shaped." (PMID 20195518, 2010). "In addition, infection of mice with Ye leads to a massive reduction of CD4+ DCs in a TLR4- and TRIF-dependent manner." (PMID 21124820, 2010).
infection (continued). "To determine whether the route of transmission affected overall viral load, CD4+ T cell decline, and competitive replication fitness of SIVmneCl8 and SIVmne027, we compared the results from the IR and IV infections." (PMID 20942954, 2010). "MHC-II-deficient mice (lacking CD4+ T cells) efficiently resolved the infection whereas MHC-I-deficient animals (MHC-I-/-; targeted mutation of the β2-microglobulin gene; devoid of CD8+ T cells) developed persistent high-level viremia." (PMID 20360949, 2010). "Therefore, it is not surprising to obtain different results with the two conditions in regard to DC-mediated trans-infection of CD4+ T cells with HIV-1." (PMID 19419540, 2009). "Animals depleted of B cells were susceptible to infection, but not if they were depleted of either CD4 or CD8 T cells." (PMID 19668372, 2009). "However, none of the three siRNAs tested had a discernable effect on enhancing infection by HIV-1 in quiescent CD4+ T-cells." (PMID 19300495, 2009). "Hence, IFN-γ produced by vaccine-primed CD4+ T cells was required for mediating adaptive immunity against both infections." (PMID 20041174, 2009). "Varying CD4 levels with constant CCR5 or varying CCR5 levels with constant CD4 consistently demonstrated that ES env clones supported lower levels of infection than the CP clones." (PMID 19360131, 2009). "However, vaccine-induced protective immunity against both infections required CD4+ T-cell-derived IFN-γ and IL-17A, and functional phagocytic effectors." (PMID 20041174, 2009). "Interestingly, during the early and intermediate phase of infection CD4/10.4 displayed significant cytolytic activity, despite only a minor expression of CD107a/b." (PMID 19529765, 2009). "Studies in the tonsil HLH model have shed light on key pathogenic properties of HIV, including cell tropism and cytopathic effects in relation to coreceptor usage, productive infection of resting CD4+ T cells, early host responses to HIV infection as well as viral coinfections." (PMID 19146681, 2009). "Activated memory CD4+ T cells are depleted from all lymphoid tissues early in infection." (PMID 19930655, 2009). "However, at later stages of the infection CD4/10.4 cells gradually lost this cytotoxic function in contrast to the CD8/10.4 cells." (PMID 19529765, 2009). "However, in CD4-depleted mice, apoptosis was also upregulated in recruited lymphocytes in spite of progressive infection." (PMID 19558669, 2009). "Prior to infection, Th17 CD4+ T cells were detected at the same frequency in AGMs and PTs." (PMID 19214220, 2009). "Similar results were obtained when infections were performed at minimal surface CD4 levels." (PMID 19360131, 2009). "Interestingly, Foxp3+CD25+CD4+ regulatory T cells are highly enriched following infection, both in the periphery and in the brain, where the virus intensively replicates." (PMID 19319188, 2009). "However, 2 weeks post infection there were 21⁄2 times more Ag85B CD4 T cells than CD8 T cells in the lungs." (PMID 19357780, 2009). "However, the percentage of CD4+CD25+Foxp3+ T cells increased significantly after the infection, following the same pattern seen in suckling mice." (PMID 19319188, 2009). "Their results were in accordance with previous studies as they were able to detect virus in HIV-1 infected animals by co-culturing infected cells with non-infected cells in vitro as well as observing a decrease in the CD4+/CD8+ ratio as early as two weeks post-infection." (PMID 19674458, 2009). "This further reaffirms that CD4+ T cells have a decisive role in resolving infection." (PMID 19727394, 2009). "Since the tetramer-based enrichment does not require in vitro antigen stimulation or other manipulations, this approach should be useful for directly measuring dynamic changes in numbers, phenotypes and differentiation of antigen-specific CD4 T cells after infections or vaccination." (PMID 19730727, 2009).
infection (continued). "The 239 envelope uses CCR5 as a co-receptor for infection of predominantly memory CD4+ T cells." (PMID 19165322, 2009). "However, a significant amount of GFP was produced by CD4+ T cells (CD3+CD4+), which peaked on day 5 post infection." (PMID 19816558, 2009). "In the extended model, however, negative feedbacks associated with both antibody and CD4+ T cells keep immune levels within a range similar to that seen for initial infection." (PMID 19727394, 2009). "The CD4 slope displayed highly significant correlation with the date of confirmed infection (Spearman's rank correlation test: rho = −0.16, p<0.001; unadjusted effect: −1.7 cells/μL/year/year, 95% CI: −2.3–−1.1), in the direction of steeper CD4 slopes over the time span of the cohort." (PMID 19478880, 2009). "At this stage, CD4 responses are deeply impaired in patients with a chronic outcome as they are weak and of narrow specificity, unlike the strong, broad and T helper 1-oriented CD4 responses associated with resolving infections." (PMID 21994550, 2009). "Time of infection is unknown for most of the patients studied so we investigated this possibility by using CD4 counts at the time of diagnosis as a proxy for the average time since infection." (PMID 19779560, 2009). "The high levels of viral replication in GALT at peak infection resulted in a profound depletion of CD4+ T lymphocytes, which could potentially lead to the immunodeficiency observed in the long term." (PMID 19930655, 2009). "Finally, our data demonstrate that the host defends itself against both infections by similar mechanisms, and that adaptive immunity to both organisms required CD4+ T cell production of both IFN-γ and IL-17A." (PMID 20041174, 2009). "While it is unlikely that SseI directly modulates the CD4+ T cell response, our data demonstrated that SseI suppressed DC migration in vivo, which correlated with the ability of Salmonella to continuously maintain a systemic infection for at least 45d." (PMID 19956712, 2009). "The relatively low net charge in the V3 loop of the CRF07_BC strain may contribute to its R5 tropism for infection of new target cells that express CD4 and CCR5." (PMID 19442296, 2009). "Thus, although we observed strong, local CD8 T cell memory, as measured by total CD8 T cell numbers, CD4 T cells preferentially accumulated (due to recruitment and/or expansion) at the site of infection." (PMID 19357780, 2009). "Similarly, infection activated CD4+ T cells in BALB/cJ mice, as shown by the increased percentage of CD69+ CD4+ T cells, but it did not activate T cells in IgD deficient mice." (PMID 19859584, 2009). "However, compared to CD8 T cells, CD4 T cells showed more extensive recruitment and were the main T cell subset proliferating at the site of infection." (PMID 19357780, 2009). "The two types of responses (CD4+ Th1 and Th2) induced by the recombinant Salmonella vector in this study are crucial for vaccines that are required to induce both cell-mediated and antibody responses for protection against infection by a number of pathogens." (PMID 19555490, 2009). "Thirdly, in contrast to CD4 T cells, macrophages are more prone to R5 infection than X4 infection." (PMID 19492063, 2009). "These include: dT, the death rate of uninfected CD4+ T cells in Model 1, set to λ/T0 to allow for steady-state pre-infection, and dn and dm the analogous death rates of uninfected CD4+ T cells in Models 2 and 3, also set so that equilibrium exists pre-infection." (PMID 19680436, 2009). "The selective nature of the infection immediately prompted speculation and the subsequent identification of the CD4 molecule as the main surface receptor for HIV entry." (PMID 20041213, 2009). "Latency establishes early after infection notably (but not only) in resting memory CD4+ T cells and involves numerous host and viral trans-acting proteins, as well as processes such as transcriptional interference, RNA silencing, epigenetic modifications and chromatin organization." (PMID 19961595, 2009).
infection (continued). "The virus was also found to replicate at this point in the infection in naive CD4+ T cells." (PMID 19930655, 2009). "We conclude that high arginase activity at the local site of infection and the consequent low L-arginine levels in nonhealer mice are associated with an impaired capacity of CD4+ T cells to produce IFN-γ." (PMID 19597544, 2009). "However, the ANRS EP32 study showed that the infection of CD4+ thymocytes and their export into the peripheral circulation is probably rare in patients on effective cART." (PMID 19876401, 2009). "Further experiences with CCR5-targeted stem cell therapies will probably encourage the treatment of selected populations of young HIV-positive patients with multi-resistant infection and exhaustion of CD4 cells, as well as HIV-infected pediatric patients with rapidly progressing disease." (PMID 19558721, 2009). "In this context, some inhibition of infection may result from the difference in the efficiency with which membrane-anchored CD4 and SCMs promote HIV-1 entry." (PMID 19343205, 2009). "The decreased expression of these genes may in part be due to depletion of circulating CD4+ T cells in PTs at 10 days post-infection, either because of increased destruction, decreased production, or movement into tissues." (PMID 19214219, 2009). "In mice, NK cells and bystander CD8+ T cells provide innate production of IFN-γ, while IFN-γ secreting, antigen-specific CD4+ T cells contribute to protection against primary infection with B. pseudomallei and following immunization with experimental vaccines in vivo." (PMID 19352426, 2009). "In contrast, rapid import may be critical in short-lived cells, such as activated CD4+ T-cells, where a 24-h delay may make the difference between productive and aborted infection." (PMID 19193229, 2009). "This increased risk was not confined to adults with low CD4 count, and was predominantly due to an increase in the disease-to-infection ratio at all stages of HIV infection." (PMID 19159487, 2009). "This is also strongly supported by CD4-depletion studies in the chimpanzee model of infection." (PMID 21994550, 2009). "CD4 co-expression with DC-SIGN (DC-specific intercellular adhesion molecule 3-grabbing nonintegrin), a C-type lectin expressed on DCs, inhibits DC-mediated trans infection by causing retention of viral particles within the cytoplasm." (PMID 19486514, 2009). "PLV infections separate from uninfected cats principally on the basis of lower CD4 counts." (PMID 19806226, 2009). "Additionally, the discrepancy in infectivity between ES and chronic clones at fixed, high CCR5 levels indicates that ES clones also require higher levels of CD4 to achieve similar infection as chronic clones." (PMID 19360131, 2009). "However, a lack of a proportional antibody response during frequent repeated infection allows for more infected cells to be produced, thus requiring higher levels of CD4+ T cells to eliminate infection." (PMID 19727394, 2009). "Furthermore, during HIV-1 productive infection, we demonstrate that autophagy is repressed in CD4 T cells but induced and regulated in macrophages." (PMID 19492063, 2009). "By uncoupling CD4+ T cell activation from ongoing infection and destruction of these cells, scSIV may facilitate the development of virus-specific CD4+ T cell responses." (PMID 19165322, 2009). "Of note, CD4+ T cell responses targeting env are strong during this early stage and are detected as early as five days post-infection, whereas env responses are rarely detected in the later stages of infection." (PMID 19165342, 2009). "Studies have shown that infection with the human immunodeficiency virus (HIV) results in increased ROS concentrations, which can in turn lead to faster progression of HIV infection, and cause CD4+ T-cell apoptosis." (PMID 19922682, 2009).
infection (continued). "We found that, relative to the rest of the study participants, individuals infected with the T242N/A146X mutants had significantly lower viral loads and higher CD4+ counts at three months post-infection (median log VL 4.53 vs. 5.09, p = 0.0077 and median CD4+ count 652.0 vs. 460.0, p = 0.0129)." (PMID 18369479, 2008). "The prevailing hypothesis to explain HIV trans-infection has been that DCs store HIV in an endocytic compartment that is subsequently delivered to the infectious synapse after engagement of a CD4 T cell." (PMID 18725936, 2008). "Expression of IL-10 mRNA was determined by real time PCR in purified splenic CD4+ T cells obtained on days 1, 3, 5 and 7 post-infection from wild type (WT) C57/BL6 mice and plasma levels of IL-10 were determined by ELISA on days 1, 3, 5 and 7 pi from WT and RAG−/− mice." (PMID 18401464, 2008). "Infection with HIV-1 causes a severe down-regulation of virus-specific CD4+ and CD8+ T cells that is not restored upon treatment with highly active antiretroviral therapy (HAART)." (PMID 18976455, 2008). "These sequences differ from those commonly found in CD4+ T cells, and do not carry any known resistance mutations, which suggests that the rare infection of a small number of progenitor cells is the most likely explanation for the observed residual viremia." (PMID 19112504, 2008). "However, to formally test the role of nTreg, mice were treated with a cocktail of anti-CD25 antibodies (previously shown to give optimal depletion of CD4+CD25hiFoxp3+cells; 25) 3 days prior to infection with PyL." (PMID 18401464, 2008). "Our studies suggest that the uninfected HIV-1 specific CD4+ T cells might be refractory to infection because they produce anti-viral CCR5 ligands and are ‘self-protected’." (PMID 18941536, 2008). "NP-2/CD4/CXCR4 cells were highly susceptible to all HIV-1 strains, except the Ba-L and SF162 strains, when tested on day 6 after infection, while NP-2/CD4/CCR5 cells were highly susceptible to five HIV-1 strains, Ba-L, GUN-1WT, GUN-4WT, GUN-7WT, and SF162, but not to the IIIB strain." (PMID 18577234, 2008). "However other explanations cannot be excluded as it is thought that the presence of HAART should prevent or at least minimise de novo infection of CD4+ T cells." (PMID 18976455, 2008). "Moreover, splenocytes from susceptible BALB/c mice, but not resistant DBA/2 mice, infected with PyNL produce IL-10 and TGF-beta during the early acute stage of infection, which is associated with an increase in the proportion of splenic CD25+ CD4 T cells." (PMID 18401464, 2008). "In the gut-associated lymphoid tissue, the largest lymphoid organ in the body and the primary site for acute HIV-1 replication, macrophages are the predominant viral reservoir following massive depletion of CD4+ memory T cells during this acute infection stage." (PMID 18241354, 2008). "The percentages of CD4+CD25+ cells increased significantly after infection with L. major." (PMID 18414636, 2008). "The fact the Sn binds HIV-1NL4-3 and facilitates trans infection raised the possibility that normal receptor CD4 and chemokine coreceptor requirements might be altered by Sn-bound HIV-1NL4-3." (PMID 18414664, 2008). "These lower initial viral loads and higher CD4+ counts at the onset of infection may slow disease progression in these individuals." (PMID 18369479, 2008). "NP-2/CD4/FPRL1 cells were found to be susceptible to the GUN-1WT, GUN-4V, and GUN-7WT cell-line-adapted HIV-1 strains: approximately 0.5, 5 and 30% of the cells became HIV-1 antigen-positive on day 6 after infection, respectively." (PMID 18577234, 2008). "The median log viral load and CD4+ count went from 4.71 copies.ml−1 (range 2.95 to 6.28) and 509 cells.ul−1 (range 255 to 1358), respectively, at three months post-infection to 4.59 copies.ml−1 (range 2.60 to 6.09) and 367 cells.ul−1 (range 202 to 1030), at twelve months." (PMID 18369479, 2008).